FLT3 (fms related receptor tyrosine kinase 3)
Diseases named in the same sentence as FLT3 in open-access papers (continued):
Sharing a sentence is not in itself a finding about the gene and the disease.
triple-negative breast carcinoma (1 paper, 2023). An invasive breast carcinoma which is negative for expression of estrogen receptor (ER), progesterone receptor (PR), and human epidermal growth factor receptor 2 (HER2). "Midostarin has been studied in triple-negative breast cancer cells, which lack FLT-3, and it has been identified as an inhibitor of aurora kinase B, leading to cell cycle arrest and apoptosis." (PMID 38132962, 2023).
trisomy (1 paper, 2023). A chromosomal abnormality consisting of the presence of one chromosome in addition to the normal diploid number. "The most frequent co-occurring somatic aberrations were by far WT1 mutations, FLT3-ITD (high ratios being associated with increased WBC count and BM blast infiltration) and trisomy 8 (85% of cases carried at least one of these aberrations and 47% had at least two)." (PMID 37085611, 2023).
trisomy 8 (1 paper, 2022). "It is usually associated with other chromosomal abnormalities, particularly trisomy 8, and other genetic mutations, such as FLT3-ITD, WT1, and CEBPA, and appears to play a role in histone methylation and acetylation." (PMID 35740427, 2022).
ZIKV infection (1 paper, 2020). "In contrast, BRAF and SOCS2, a FLT3 interactor, were unregulated upon ZIKV infection." (PMID 33148605, 2020). "Based on the observations above drawn from the ZIKV map, we hypothesize that FLT3 or BRAF are the effective targets of Sorafenib in ZIKV infection, rather than VEGFR and PDGFR." (PMID 33148605, 2020).
Zinc deficiency (1 paper, 2025). A deficiency of the essential metal Zinc; an essential cofactor for many enzymes. "Even zinc deficiency alone resulted in decreased phosphorylation of STAT3 and FLT3 in MV4‐11 and THP‐1 (data not shown)." (PMID 40583520, 2025).
tumor (444 papers, 2006 to 2026). "Tumor cells from patients with FLT3 mutations activate various signaling proteins, including STAT5, RAS/MAPK, and PI3K/AKT, along with abnormal upregulation of AURORA kinase." (PMID 40016600, 2025). "In view of its promising anti-tumor effects and safety profile, fucoxanthin represents a candidate worthy of further exploration for FLT3-mutated subtypes." (PMID 40735485, 2025). "One plausible explanation is that mutations in epigenetic modifiers (e.g. DNMT3A) are likely initiating events, whereas those in signaling genes (e.g. FLT3) drive rapid tumor growth, resulting in diagnosis with fewer subsequent mutations." (PMID 40662787, 2025). "Targeting both AXL and FLT3 with gilteritinib results in tumor regression and decreased proliferation in FLT3 mutation-positive AML models, both in vitro and in vivo." (PMID 39367387, 2024). "Quizartinib, a potent and specific oral FLT3 inhibitor, exerts an anti-cancer effect by inhibiting the activity of the mutation-activated FLT3, which causes tumor cells to undergo apoptosis." (PMID 38530400, 2024). "The FLT3 c.2541+58 A > G (V1) and FLT3 c.2053+85_2053+88del (V2) polymorphisms were chosen as markers, which were heterozygous in donor cells and homozygous in patient cells, including tumor cells, as found in the sample before HSCT." (PMID 37684264, 2023). "Activating mutations in the FLT3 gene are common among patients and make the tumour susceptible to FLT3 inhibitors, but resistance to such inhibitors develops quickly." (PMID 37568211, 2023). "FLT3 represents a member of the class III receptor tyrosine kinase family, and somatic mutation and amplification of FLT3 is an important phenomenon associated with tumour development in solid tumours." (PMID 37076508, 2023). "In AML cells, CDDD11-8 suppressed the proliferation and caused robust inhibition of tumor growth in vivo via synergistic inhibition of FLT3." (PMID 35267421, 2022). "Here we investigated the potency of VRP encoding FLT3 as a therapeutic vaccine in mouse hematolymphoid tumor models." (PMID 35686131, 2022). "Since Ras mutations can activate the MAPK and PI3K-AKT pathways, some tumor patients are also resistant to these novel FLT3 inhibitors." (PMID 35684449, 2022). "The enrichment analysis indicated that FLT3 participate in immune-associated pathways like complement pathway, which displayed anti-tumor capacity in mouse BC models." (PMID 36159964, 2022). "Our results corroborate that intra‐tumour plurality of FLT3‐ITD mutations at time of diagnosis is a frequent characteristic of FLT3‐ITD mutated AML." (PMID 33817952, 2021). "Another study showed that FLT3-ITD mutation was present in the primitive cells, whereas FLT3-TKD mutation was present in the more differentiated cells within the same tumor." (PMID 34660311, 2021). "CBL is an E3 ubiquitin ligase that targets both active β-catenin and FLT3 (fms related receptor tyrosine kinase 3): two factors important for tumor-induced angiogenesis which have also been implicated in AML." (PMID 33987182, 2021). "This includes the consideration of stem cell transplant after first remission for the primitive subset of NPM1-mutated AML cases whose tumor cells lack a FLT3-ITD mutation." (PMID 33594052, 2021). "Anyhow, since this approval and because FLT3 mutated patients present with a high tumor burden at diagnosis, the results of FLT3 mutational screen must been found rapidly." (PMID 35845213, 2021). "Midostaurin (PKC412), an FLT3 inhibitor, first approved by the FDA for treatment of AML patients with FLT3 mutations, suppresses the survival of ES cells and tumor growth in mice." (PMID 32754598, 2020). "A range of mechanisms are observed, including down‐regulation of activatory receptors on NK cells, reduction of NK ligands on the tumour and decreased production of the potent NK‐stimulatory cytokine IL‐15, secondary to acquisition of the FLT3 mutation." (PMID 31823351, 2020).
tumor (continued). "Targeting AXL and FLT3 with gilteritinib translated to tumour regression and reduced proliferation in FLT3 mutation-positive cellular and mouse models of AML." (PMID 31684958, 2019). "The FLT3 gene was mutated in 1 tumor (1.1%), showing one novel missense mutation in the protein tyrosine kinase domain." (PMID 31548566, 2019). "miR-139-5p was found downregulated in CN-AML with mutated FLT3, and acted as tumor suppressor in a primary AML transplant model." (PMID 29401684, 2018). "Regardless of the underlying mechanisms inducing expression of PIMs in these FLT3-WT AMLs, we show that their inhibition triggers cell death in vitro and tumor growth inhibition in vivo with similar efficacy as in cells bearing FLT3-ITD mutations." (PMID 29682194, 2018). "These experiments verified that palbociclib is not only able to inhibit cell growth in vitro but also blocks tumor formation in vivo in the context of FLT3 kinase domain mutation." (PMID 30544932, 2018). "For example, oncodriveFM missed FLT3 due to a cluster of medium impact mutations and OncodriveCLUST missed several tumor suppressor genes, since loss of function mutations in these genes do not necessarily cluster (e.g. PBRM1)." (PMID 29030609, 2017). "Exome sequencing of Tet2−/− tumours reveals accumulation of numerous mutations, including Apc, Nf1, Flt3, Cbl, Notch1 and Mll2, which are recurrently deleted/mutated in human haematological malignancies." (PMID 28440315, 2017). "AML patients positive for FLT3-ITD mutation along with reduced BEX1 expression displayed poor overall survival suggesting that BEX1 acts as a tumor suppressor in AML." (PMID 26046670, 2015). "Treatment of FLT3-mutated xenografted model displayed dose-dependent and significant tumor cell growth inhibition." (PMID 25110867, 2014). "However, fusion with ETS variant transcription factor 6 (ETV6) produces an ETV6/FLT3 oncoprotein fusion that is constitutively active and utilizes Hsp90, a chaperone known to stabilize a number of proteins required for tumor progression." (PMID 38825690, 2024). "A high frequency of FLT3-ITD somatic mutations in dogs with neoplastic mast cells elevated the WBC count, along with an increase in neutrophil subpopulations, corresponding to human AML patients harboring FLT3-ITD mutations with high tumor burden and poor clinical outcomes." (PMID 36072760, 2022). "Thus, here we demonstrate for the first time that VRP encoding FLT3 can promote a polyclonal B cell response to not only the encoded TAA but also other TAAs expressed on tumor cells." (PMID 35686131, 2022). "Genetic tests of tumor tissue revealed the presence of the the FLT3-ITD mutation." (PMID 35875115, 2022). "Indeed, certain studies have demonstrated that the co-existence of WT-FLT3 attenuated the anti-tumor effects of FLT3 inhibitors on FLT3-mutated AML cells in vitro and in vivo." (PMID 32722298, 2020). "Moreover, BGB324 demonstrated anti-tumor activity in FLT3 wild-type as well as FLT3-mutated AML cells." (PMID 31694201, 2019). "Both drugs showed synergistic anti-tumor effects in a human FLT3/ITD-mutated AML cell line." (PMID 30514344, 2018). "Thus, the intra-tumor heterogeneity and multiple mutations are important contributors in the relapse and FLT3 inhibitor resistance." (PMID 29262547, 2017). "MV4;11 tumor is known to be driven by the tyrosine kinase receptor Flt3-ITD mutation." (PMID 25671299, 2015). "In conclusion, our results taken together suggest that FLT3 mutations may lead to activation of mTOR signaling pathway and thus contribute to tumor cell survival and growth in AML." (PMID 21067588, 2010). "Moreover, gilteritinib promotes apoptosis in FLT3–ITD mutations carrying tumor cells in vitro." (PMID 37297842, 2023).
tumor (continued). "CARs used in AML often targeted CD123 and CD33; development of more diverse targets, including cell signaling of tumor growth (FLT3, NKG2D, TIM3, FRβ), addressed heterogeneity." (PMID 42109662, 2026). "Following tumor cytoreduction and lymphodepletion, 1 × 106/kg of FLT3 CAR-T cells were administered, resulting in in vivo CAR-T cell expansion and grade 1 cytokine release syndrome in both patients." (PMID 42129518, 2026). "The CAR‐DC cells with an FLT3‐integrated intracellular domain enabled conventional DC differentiation and enhanced cross‐presentation of tumour antigens." (PMID 41292193, 2025). "Tandutinib is a multi-kinase inhibitor that targets FLT3 and PDGFR signaling, both of which are implicated in immune suppression and tumor–stroma interactions." (PMID 40826334, 2025). "PDAC: It can reduce the number and activity of tumor-friendly M2 macrophages and up-regulate the expression of FLT3, a key gene that affects the function of DC cells, thereby improving the immune status of TME." (PMID 40161377, 2025). "Sorafenib inhibited multiple receptor tyrosine kinases involved in tumor signaling and apoptosis including FLT3, RET, KIT, VEGFR, and PDGFR by directly blocking auto-phosphorylation." (PMID 41226551, 2025). "In vivo,CC-90009 and quizartinib combination also shows higher anti-tumor effect andprolongs survival in an FLT3-ITD-positive AML PDX mouse model compared to the singletreatments." (PMID 41270153, 2025). "Taken together, the poor pharmacokinetics of 20D9h3-DUBA in mice is especially problematic for a low expressed target like FLT3 and can highly underestimate its anti-tumor effect." (PMID 39870768, 2025). "Although AML is typically characterized by a low mutation burden, certain high-frequency driver mutations, such as FLT3-ITD and NPM1 mutations, can generate immunogenic peptides that act as tumor-specific antigens, triggering targeted immune responses." (PMID 40861464, 2025). "Sorafenib hinders the inhibition of tyrosine kinase receptors such as VEGFR-2, VEGFR-3, PDGFR-β, EGFR, c-Kit, and Flt3, which ultimately impedes the proliferation of tumor cells and angiogenesis." (PMID 41050183, 2025). "This suggested that Flt3 was a promising target gene for activating ferroptosis in MDSCs to exert anti-tumor immunity." (PMID 40796725, 2025). "It exerts its antitumor activity by inhibiting multiple receptor tyrosine kinases, including KIT, PDGFRA, PDGFRB, VEGFRs, RET and FLT3, thereby targeting both tumor cell proliferation and angiogenesis." (PMID 40733131, 2025). "In this research, the levels of VEGFR-2, VEGFR-3, PDGFR, c-Kit and Flt3 were assessed in tumor tissues treated with various methods (at the specified dose and duration)." (PMID 41050183, 2025). "Expression of cell-cycle specific genes suggested KF cells were more frequently in S and G2/M phase, thereby linking high levels of FLT3 with tumor cell proliferation in relapsed/refractory ETP-ALL." (PMID 39849166, 2025). "The secretion of TNF by macrophages is decreased in patients with FLT3-ITD mutations, but TNF exerts a dual effect on tumor cells." (PMID 40861464, 2025). "Western blot analysis revealed that IHCH9033 treatment led to increased AcH3, along with elevated γH2AX and cleavage of caspase 3 in FLT3-ITD tumor tissues." (PMID 39955584, 2025). "Selecting the appropriate intracellular domain (e.g., 4‐1BB, FLT3 or CD40) of CAR can induce the mature phenotype of CAR‐DC when recognising the tumour, and overcome the acclimation of tolerant DC cells by the suppressive TME." (PMID 41292193, 2025). "GO enrichment and pathway analyses of the top 500 DEGs in KF cells revealed a proliferative and inflammatory-related transcriptional profile similar to tumor cells expressing high levels of FLT3 in primary relapsed/refractory ETP-ALL." (PMID 39849166, 2025). "Multiple studies in cancer immunotherapy are investigating strategies to expand cDC1 in the tumor through use of a soluble recombinant Flt3 protein, CDX-301." (PMID 38829139, 2024).
tumor (continued). "Similar to quizartinib and gilteritinib, the combination of azacitidine with sorafenib also synergistically inhibited MOLM-13 and MV4-11 cell growth, induced apoptosis, and decreased tumor volume in xenograft mouse model of FLT3-ITD AML." (PMID 38696033, 2024). "In the MB49 tumor model, flow cytometry analysis revealed a higher proportion of FLT3+ phenotype CD8+ T cells in tumor-derived CD8+ T cells compared to spleen-derived CD8+ T cells." (PMID 38213738, 2024). "This suggests a potentially significant role for FLT3 amplification not only in CRC but also in targeted therapies across various tumor types." (PMID 39011472, 2024). "The Y842 mutation in the FLT3-ITD background impairs the RAS/ERK pathway and delays tumor formation." (PMID 39273530, 2024). "Our previous studies showed that FLT3 inhibitors loaded on Pluronic–gold nanoparticles inhibit tumor growth and have a superior therapeutic effect compared to bare drugs." (PMID 38799169, 2024). "In AML, the FLT3 mutation was significantly associated with NUP98 fusions and indicated a higher tumor burden." (PMID 39273530, 2024). "Perhaps this downregulation is part of a broader reprogramming of the tumor microenvironment that is not fully understood, which is why we recommend the relationship between galectins and FLT3 be further explored." (PMID 38927753, 2024). "NK cells were the rarest in tumor microenvironment infiltration but significantly more common in the FLT3‐high group; value – 3.28, 3.46 for the FLT3‐low group and 7.74, 6.20 for the FLT3‐high group for LUSC and LUAD, respectively." (PMID 38327131, 2024). "Tumor-infiltrating TAMs have an increased expression of immunosuppressive markers, including fms-like tyrosine kinase 3 (FLT3) and transforming growth factor beta (TGFβ)." (PMID 38727262, 2024). "In conclusion, our study, the first of its kind, analyzes genomic material from 1016 NSCLC cases and shows the effect of high expression of FLT3 on tumor microenvironment." (PMID 38327131, 2024). "Next, we conducted pharmacokinetic and pharmacodynamic studies to confirm that the inhibition of FLT3 controlled tumor growth in vivo." (PMID 38950330, 2024). "Reduced tumor burden in FLT3‐ITD AML‐bearing mice was observed with interventions utilizing low‐sucrose and/or low‐fat diets, or time‐restricted feeding (TRF) compared to mice fed normal chow ad libitum." (PMID 38334474, 2024). "FLT3 is a receptor tyrosine kinase, and its inhibition has been shown to reduce tumor size in HCC, making it a promising therapeutic target for treatment." (PMID 39273340, 2024). "This illustrates the complex tumor microenvironment of AML and highlights the need for further investigation into the effects of FLT3-ITD mutations on DC phenotypes and their downstream effects on Th polarization." (PMID 38495876, 2024). "Mouse xenograft models created using MOLM-13 and EOL-1 cells followed by injection of human CD3+ T cells showed a significant reduction in tumor growth with weekly FLT3 BiTE treatment." (PMID 39697225, 2024). "Mivavotinib (TAK‐659/CB‐659), a dual SYK/FLT3 inhibitor, reduced immunosuppressive immune cell populations and suppressed tumor growth in combination with anti‐PD‐1 therapy in cancer models." (PMID 38501219, 2024). "It has also been found that the high expression of PLA2G4A in FLT3-mutated AML is not only an indicator of poor prognosis but also related to drug resistance to tyrosine kinase inhibitors and changes in the tumor microenvironment of AML." (PMID 38033488, 2023). "MET was only quantifiable in two tumour samples, while FLT3 was only quantifiable in 1 tumour sample." (PMID 36890818, 2023). "The effect of emavusertib on tumor growth was evaluated in vivo in the subcutaneous MV4-11 and MOLM-14 AML tumor models which harbor FLT3-ITD mutations and are sensitive to FLT3 inhibitors in cell-based assays and subcutaneous tumor xenograft model studies." (PMID 37954584, 2023).